ECM1 (extracellular matrix protein 1)
Description:
Involved in endochondral bone formation as negative regulator of bone mineralization. Stimulates the proliferation of endothelial cells and promotes angiogenesis. Inhibits MMP9 proteolytic activity.
Synonyms: URBWD
Tractability: Antibody: its Gene Ontology location is reachable by antibodies, with high confidence; UniProt places it where antibodies can reach, with medium confidence; UniProt predicts a signal peptide or a membrane-spanning region.
Gene: Protein-coding gene on chromosome 1 (150,507,989 to 150,513,789, forward strand). Ensembl gene ENSG00000143369.
Subcellular location: Secreted, extracellular space, extracellular matrix
Subcellular location (Human Protein Atlas): Cytosol; Nucleoplasm; Predicted to be secreted
Pathways (Reactome):
Hemostasis: Platelet degranulation
Gene Ontology:
Molecular function: protease binding; protein binding; extracellular matrix structural constituent; interleukin-2 receptor binding
Biological process: negative regulation of bone mineralization; negative regulation of peptidase activity; positive regulation of angiogenesis; positive regulation of canonical NF-kappaB signal transduction; positive regulation of endothelial cell proliferation; regulation of bone mineralization; signal transduction
Cellular component: extracellular exosome; extracellular matrix; extracellular region; non-collagenous component of interstitial matrix; platelet dense granule lumen
Genetic constraint (gnomAD): Loss-of-function variants: 58 observed, 68.7 expected, observed/expected ratio (o/e) 0.84, 90% interval 0.68 to 1.05. The upper end of that interval is the gene's LOEUF score, 1.05, which puts it in group 4 of 6, group 1 being the genes least tolerant of losing a copy. Missense variants: 646 observed, 719.5 expected, observed/expected ratio (o/e) 0.9, 90% interval 0.84 to 0.96. Synonymous variants: 237 observed, 273.03 expected, observed/expected ratio (o/e) 0.87, 90% interval 0.78 to 0.97.
Homologues: Orthologues: chimpanzee ECM1 (99% identical), macaque ECM1 (94% identical), pig ECM1 (77% identical), dog ECM1 (75% identical), rabbit ECM1 (75% identical), rat Ecm1 (70% identical), mouse Ecm1 (69% identical), guinea pig ECM1 (68% identical), tropical clawed frog ecm1 (26% identical), zebrafish ecm1b (24% identical), zebrafish ecm1a (11% identical).
Diseases named in the same sentence as ECM1 in open-access papers:
ECM1 is named in the same sentence as 153 diseases in open-access papers, as found by Europe PMC text mining. Sharing a sentence is not in itself a finding about the gene and the disease. The quoted sentences say what the papers report.
breast carcinoma (39 papers, 2012 to 2025). "Significantly, higher expression of ECM1 is associated with poor response to endocrine therapies in luminal B breast cancer patients." (PMID 35784388, 2022). "ECM1 regulates breast cancer cell invasion by inducing the expression of genes associated with the progression of EMT." (PMID 35116193, 2022). "ECM1 is located in the 1q21 locus that is frequently amplified in breast cancers and associated with worse clinical outcomes." (PMID 35784388, 2022). "The present study showed that overexpression of ECM1 is associated with worse clinical outcomes and endocrine resistance to ER+ breast cancer." (PMID 35784388, 2022). "In this study, we found that ECM1 is genetically amplified, and its overexpression is significantly associated with a worse prognosis in ER+ breast cancers." (PMID 35784388, 2022). "Increased fibulin 1 and ECM1 have been associated with different malignancies, and, in cases of breast cancer, it was shown to elicit a TH2 response." (PMID 35386989, 2021). "In particular, ECM1 is implicated in breast cancer, thyroid cancer, hepatocellular carcinoma and other cancers and also in ulcerative colitis." (PMID 34563241, 2021). "Next, we investigated whether high expression of ECM1 is associated with a poor prognosis of luminal breast cancers." (PMID 35784388, 2022). "In addition, we found that high expression of ECM1 is associated with worse outcomes in METABRIC ER+ breast cancers treated with endocrine therapy." (PMID 35784388, 2022). "Extracellular matrix protein 1 (ECM1) is associated with a poor prognosis of breast cancers." (PMID 35784388, 2022). "Finally, we showed that the expression of ECM1 in ER+ breast cancer is strongly associated with the phosphorylation of Src in ER+ breast cancer cells." (PMID 35784388, 2022). "ECM1 was linked with angiogenesis and metastasis of breast cancer cells, but this gene may be responsible for metastasis of EOC." (PMID 30970615, 2019). "Moreover, the Kaplan-Meier plots constructed using datasets from HER2-positive breast cancer patients demonstrated a significant association of ECM1 expression with poor outcome." (PMID 25499743, 2014). "This suggests that ECM1 is associated with breast cancer cells that have a potential for metastasis, although the exact mechanism remains unclear." (PMID 22284579, 2012). "To explore whether ECM1 expression was associated with the metastatic character of the breast cancer cells, we analyzed the ECM1 expression profiles between the primary tumors and the metastatic foci in individuals with metastasis." (PMID 22284579, 2012). "In breast cancer (BC), overexpressing ECM1 increases matrix metalloproteinase 3 (MMP3) and S100A/B protein levels." (PMID 38402239, 2024). "In order to further confirm the pro-metastatic effects of ECM1, we conducted an experiment where ECM1 was overexpressed in human breast cancer cells (HCC1806)." (PMID 38402239, 2024). "It has also been shown that in breast cancer, ECM1 can regulate the actin cytoskeleton structure of invasive breast cancer cells through the regulation of S100A4 and Rhoa." (PMID 39418248, 2024). "Here, the authors show that under obesity conditions, increased extracellular matrix protein 1 protein levels in circulating small extracellular vesicles induce breast cancer growth and metastasis." (PMID 38402239, 2024). "The results of the study indicate that uEVs, which contain ECM1 and ANXA1, have the potential to be used as diagnostic biomarkers for breast cancer." (PMID 39040439, 2024). "The study presented here corroborates the elevated levels of ECM1 observed in uEVs of breast cancer patients." (PMID 39040439, 2024). "This indicates a potential correlation between ECM1 expression and the development and progression of this subtype of breast cancer." (PMID 39040439, 2024). "ECM1 is a secreted glycoprotein reported to be a marker of poor prognosis in multiple cancer types, including breast cancer." (PMID 37116492, 2023).
breast carcinoma (continued). "It was reported that ECM1 induces tumor growth by promoting angiogenesis or enhancing the EGF signaling in the breast cancer." (PMID 36765767, 2023). "ECM1 protein levels are higher in breast cancer samples than in normal breast epithelium and have been associated with increased lymphatic microvessel density in breast cancer patients." (PMID 35821197, 2022). "ECM1 is overexpressed in luminal breast cancer patients compared to the basal type of breast cancer." (PMID 35784388, 2022). "To validate the induced ECM1 following endocrine therapy, we next determined the expression of ECM1 in ER+ breast cancer cells grown in the estrogen-deprived condition." (PMID 35784388, 2022). "To investigate the expression level of ECM1 in ER+ breast cancers, we analyzed the transcriptome data from The Cancer Genome Atlas (TCGA) and METABRIC breast cancers by subtypes classified by PAM50." (PMID 35784388, 2022). "We next assessed the functional role of ECM1 in ER+ breast cancer cells that acquire endocrine resistance." (PMID 35784388, 2022). "Herein, we identified that ECM1 that is genetically amplified in breast cancers is crucial for the survival of ER+ breast cancer cells with the acquired endocrine resistance." (PMID 35784388, 2022). "These suggest that ECM1 is amplified and consequently overexpressed in breast cancers, including luminal subtypes." (PMID 35784388, 2022). "Consistently, the expression level of ECM1 is significantly higher in luminal subtypes than in other subtypes in METABRIC breast cancers." (PMID 35784388, 2022). "Based on these findings, we strongly suggest that ECM1 significantly contributes to the acquisition of endocrine resistance in ER+ breast cancers by the activation of Src." (PMID 35784388, 2022). "Collectively, these imply that ECM1 contributes to the activation of Src, which promotes cell proliferation and endocrine resistance in ER+ breast cancer cells." (PMID 35784388, 2022). "Collagen proteins promote metastasis of breast cancer cells, while ECM1 is a key player in triggering EMT and metastasis of breast cancer cells through stabilization of β-catenin." (PMID 32484822, 2020). "Extracellular matrix protein 1 (ECM1) is an important prognosis marker for the invasion of breast cancer as well as migration and drug resistance." (PMID 32426267, 2020). "The important ECM proteins like integrins (b1-, b5-, and b6- integrins), ECM1 protein, and Hic-5 protein are also actively involved in breast cancer development." (PMID 29983921, 2018). "Cytoplasmic ECM1 expression seems preferentially expressed in metastatic epithelial tumors, and it has been observed in breast cancer, thyroid carcinoma, laryngeal carcinoma, etc.." (PMID 27460906, 2016). "In fact, differences in expression of ECM-related genes have been used to stratify breast carcinomas into four groups, where the subgroup ECM1 have the worst prognosis." (PMID 27350877, 2016). "To further confirm MMP9 as a mediator of ECM1-dependent effects, we treated breast cancer cells with recombinant human MMP9 (rhMMP9)." (PMID 25499743, 2014). "ECM1 has important roles in both cancer development and trastuzumab resistance in breast cancer through activation of EGFR signaling." (PMID 25499743, 2014). "We evaluated the relationship of ECM1 expression to Ttzm resistance in breast cancer cells using cytotoxicity as a marker of the drug’s effectiveness." (PMID 25499743, 2014). "Increasing ECM1 protein level predicted shorter distant metastasis-free survival in HER2-positive breast cancer patients (left)." (PMID 25499743, 2014). "In this study, we investigated the role of ECM1 in oncogenic cell signaling in breast cancer, and potential mechanisms for its effects." (PMID 25499743, 2014). "Our findings are clinically relevant in identifying ECM1 as an unfavorable prognostic marker in HER2-positive breast cancer." (PMID 25499743, 2014).
breast carcinoma (continued). "We recently showed that differential expression of extracellular matrix (ECM) genes delineates four subgroups of breast carcinomas (ECM1, -2, -3- and -4) with different clinical outcome." (PMID 23441215, 2013). "ECM1 expression was positively correlated with estrogen responsiveness and the metastatic properties of breast cancer." (PMID 22284579, 2012). "We further analysed the LMVD in breast cancer tissue and lymph nodes for both ECM1 and VEGF-C staining." (PMID 22284579, 2012). "In the present study, cytoplasmic ECM1 was significantly elevated in breast cancer specimens, compared to the peritumoral normal counterparts from the same patients." (PMID 22284579, 2012). "The rate of ECM1 positive staining in breast cancer tissues was higher (31/41, 75.6%) than that in the corresponding epithelial tissues (4/41, 9.8%, P < 0.001) and lymph nodes (13/41, 31.7%, P < 0.001)." (PMID 22284579, 2012). "Nevertheless, our findings support a potential role for ECM1 in the lymphatic progression of breast cancer, an area that will require further study to explore the mechanisms involved." (PMID 22284579, 2012). "It has been reported that ECM1 was over-expressed in many solid tumors, such as breast cancer, thyroid cancer, cholangiocarcinoma, lung cancer, bladder cancer, ovarian cancer, colorectal cancer, and was related to chemo-resistance, tumor invasion, metastasis and poor prognosis." (PMID 38546916, 2024). "We speculate that ECM1 may play a role in the regulation of biological behaviour of breast cancer cells by CAF-S4 subpopulation cells, but the exact mechanism still needs to be explored." (PMID 39418248, 2024). "Our results suggest that ECM1 and ANXA1 in uEVs could potentially serve as diagnostic biomarkers for breast cancer." (PMID 39040439, 2024). "Our study found elevated levels of ECM1 in uEVs of breast cancer patients." (PMID 39040439, 2024). "Furthermore, extracellular matrix protein 1 (ECM1), microtubule-associated serine/threonine kinase family member 4 (MAST4), and Filaggrin (FLG) exhibit heightened levels in the urine of breast cancer patients." (PMID 38250812, 2023). "Moreover, ECM1, MAST4, FLG, and MAST4 are implicated as potential biomarkers for the preliminary indication of breast cancer presence." (PMID 38250812, 2023). "Besides this, ID4, SEMA3F, FOXD, KCNK5, WNK4 and ECM1 associate with chemoresistance origin and SOX5, ITM2A, SNCG, EPHA4, NTS, FGFR2 and ENPEP associate moreover with breast cancer tumorigenesis." (PMID 37239828, 2023). "One study found that ECM1 was expressed in the human breast cancer cell lines MDA-435 and LCC15, both of which are highly tumorigenic, and the results suggest that ECM1 has angiogenic properties and may promote tumor development." (PMID 37872487, 2023). "Interestingly, high expression of ECM1 was strongly associated with short RFS and OS in luminal B breast cancer patients following endocrine therapy." (PMID 35784388, 2022). "To gain more insight into this notion, we assessed whether the expression level of ECM1 is prognostic in ER+ breast cancers treated with endocrine therapy." (PMID 35784388, 2022). "Finally, an interrogation of a dataset containing transcriptome and proteome of breast cancer cell lines revealed that the level of ECM1 mRNA is positively correlated with that of phosphorylated Src." (PMID 35784388, 2022). "Our findings propose the implication of ECM1 for endocrine resistance in ER+ breast cancers." (PMID 35784388, 2022). "We show that ECM1 promotes endocrine resistance in ER+ breast cancers." (PMID 35784388, 2022). "Thus, we examined the copy number alteration (CNA) of the ECM1 in ER+ breast cancers within datasets available in cBioPortal." (PMID 35784388, 2022). "Moreover, we validated the antitumour effect on HLA-A2.1+/ECM1+ murine breast cancer cell-bearing mouse model." (PMID 33910591, 2021).
breast carcinoma (continued). "More interestingly, ECM1 may regulate the actin cytoskeletal architecture, leading to metastasis of aggressive breast cancer cells." (PMID 34244494, 2021). "HLA-A2.1 and human ECM1 double-knock-in mouse mammary cancer cell line (E0771) was subcutaneously injected in HLA-A2.1 transgenic mice to construct an allograft tumour model for investigating the immune activation and the antitumour effects induced by LA under the same condition." (PMID 33910591, 2021). "In addition, ECM1 promoted aggressive phenotype of breast cancer by recruitment of MSN to promote its activation for invadopodia formation, which was closely correlated with breast cancer invasion." (PMID 31335317, 2019). "In a recent study, ECM1 was shown to enhance the proliferation of breast cancer cells." (PMID 28160560, 2017). "Our findings showed that ECM1 may influence cell proliferation and Ttzm resistance in human breast cancer cells through augmentation of EGF signaling." (PMID 25499743, 2014). "The anti-ECM1 antibodies also inhibited cell proliferation in other breast cancer cell lines." (PMID 25499743, 2014). "To test whether galectin-3 secreted into the culture medium was related to ECM1 action, we treated cultured breast cancer cells with rhECM1." (PMID 25499743, 2014). "It will be interesting to see whether ECM1 could become a new target for breast cancer hormonotherapy." (PMID 22284579, 2012). "In these dysfunctional ORGs, combined with relevant researches, ABCG1 is a potential target for treating ovarian cancer associated with ECM1-activated signaling, while LEPR is the one of breast cancer risk factors, indicating ORGs might play important roles in PRAD." (PMID 37788005, 2023). "We showed that the level of ECM1 mRNA is strongly and positively correlated with that of phosphorylated Src at Y416 residue, a surrogate marker for its activation, in ER+ breast cancer cells, suggesting that ECM1 may promote endocrine resistance by the activation of Src." (PMID 35784388, 2022). "Therefore, phosphorylation of myosin may contribute to signaling downstream of the ECM1-integrin αXβ2 interaction, which is to a certain extent consistent with a report showing that ECM1 regulates the actin cytoskeletal architecture of breast cancer cells." (PMID 34244494, 2021). "A number of current studies have shown that ECM1 could promote tumor cell proliferation and invasion in malignant tumors, including digestive system, respiratory system, breast cancer, and melanoma." (PMID 34970146, 2021). "It was also reported that ECM1 could be an important prognostic marker in patients with breast cancer or with hepatocellular cancer, which indicated that detecting abnormal expression of this protein would be useful to predict an unfavorable prognosis in malignancy." (PMID 24779890, 2014). "Moreover, tissues and sera of patients with breast cancer were used to confirm the effect of ECM1." (PMID 25499743, 2014). "Therefore, like VEGF-C, ECM1 appears to be a potent enhancer of tumor lymphangiogenesis and may contribute to an increased rate of metastatic spread of breast cancer cells to the lymph nodes." (PMID 22284579, 2012). "The expression levels of ECM1 and ANXA1 were also confirmed in the uEVs of MMTV-PyMT transgenic breast cancer mouse models." (PMID 39040439, 2024). "The findings indicated a significant decrease in the levels of ECM1 and ANXA1 in the uEVs of breast cancer patients after surgery, compared to before surgery." (PMID 39040439, 2024). "The uEVs were found to contain ECM1 and ANXA1, which were validated by CLIA as effective markers for discriminating breast cancer patients from healthy controls or patients with benign breast nodules." (PMID 39040439, 2024). "This study has several limitations, as it included a small number of participants, even though the current data suggest the potential of ECM1 and ANXA1 in the uEVs to distinguish breast cancer patients." (PMID 39040439, 2024).